LRP1 (LDL receptor related protein 1)
Diseases named in the same sentence as LRP1 in open-access papers (continued):
Sharing a sentence is not in itself a finding about the gene and the disease.
Alzheimer disease (continued). "Furthermore, astrocytic LRP1 is necessary for the degradation of Aβ and the reduced accumulation of amyloid plaques in Alzheimer’s disease." (PMID 33519378, 2020). "Lrp1 is vital for the production, internalization and catabolism of amyloid β, and in the brains of Alzheimer’s disease patients, according to some studies, Lrp1 levels are significantly reduced." (PMID 30931303, 2019). "Moreover, low levels of LRP1 have been observed in Alzheimer’s disease patients, in certain cancers, in cases of reduced glucose uptake and metabolism and in certain cardiovascular pathologies." (PMID 29201005, 2017). "For instance, decreased expression of LRP1 has been hypothesized to be crucial in the extracellular accumulation of beta amyloid protein occurring during Alzheimer’s disease." (PMID 26031516, 2015). "In neurons, LRP1 is predominantly expressed in the postsynaptic region and the cell body, where it regulates lipid transport and the metabolism of amyloid-β (Aβ) peptides whose accumulation is considered central to the pathogenesis of Alzheimer's disease (AD)." (PMID 25500815, 2014). "In neurons the most important are LRP-1 and LRP-2, even it is thought that a causal factor in Alzheimer's disease (AD) is the malfunction of this process which cause impairment intracellular signaling as well as storage and/or release of nutrients and toxic compounds." (PMID 22934024, 2012). "The low-density lipoprotein receptor related protein 1 (LRP1) has been implicated in Alzheimer's disease (AD) but its signalling has not been fully evaluated." (PMID 20205790, 2010). "AEP and LRP‐1 both influence the regulation of the extracellular matrix, Aβ deposition, and apolipoprotein E (ApoE) synergy, which indicates that these two proteins may exist in the crosslink between vascular disease and Alzheimer's disease." (PMID 40116141, 2025). "Thus, the regulation of LRP1 in the liver is a promising target for Alzheimer’s disease therapy, and LRP1 activators, such as plant extracts, anti-diabetic drugs, and statins, may form the basis for further development of new therapeutic approaches." (PMID 39456746, 2024). "Its broad expression and multifunctionality make LRP1 involved in many physiological and pathological processes, including the regulation of the extracellular matrix, transportation across the blood-brain barrier, coagulation, inflammation, lipid metabolism, Alzheimer’s disease, and atherosclerosis." (PMID 37153545, 2023). "By using the 2602 healthy controls from the Alzheimer’s Disease Sequencing Project (ADSP) (NIAGADS) as a control for background population variation, we demonstrated a significant association of rare, potentially damaging LRP1 variants with CHD, especially CTD." (PMID 37107705, 2023). "In addition, changes in LRP1 may have roles in dementia and Alzheimer’s disease (AD) progression, as does NOTCH4." (PMID 31026304, 2019). "The fluorescent peptide Aβ1-42 (FAM-Aβ1-42) is one of the hallmarks of Alzheimer’s disease patients and this peptide was previously demonstrated to have a high affinity for LRP1 Moreover, hepatic cells have an important role in the clearance and uptake of systemic Aβ via LRP1 endocytosis." (PMID 29201005, 2017). "LRP1 is a large multiligand receptor involved in several cellular processes, including intracellular signalling, lipid homeostasis including cholesterol transport, and clearance of apoptotic cells and thought to have a role in the pathology of Alzheimer disease (AD)." (PMID 26396182, 2015). "Collectively, these data suggest that LRP1 could be a crucial factor in Alzheimer's disease and the receptor characteristics of LRP1 make this protein a potential "drugable" target where influencing the binding of LRP1 to any of its ligands could be a useful therapeutic." (PMID 22537779, 2012).
Alzheimer disease (continued). "In the central nervous system (CNS), LRP1 is highly expressed in neurons and plays critical roles in lipoprotein metabolism, neurotransmission, synaptic plasticity, cell survival, and clearance of the amyloid-β (Aβ) peptide, critical in the pathogenesis of Alzheimer's disease (AD)." (PMID 21264353, 2011). "The selective knock-out of Lrp1 in astrocytes results in an accumulation of Aβ-peptide in the CNS and exacerbates disease development in APP/PS1 mice, an established model of Alzheimer disease." (PMID 37383546, 2023). "The LRP1 and the LRP2 receptor are discussed as important modulators in the context of the Alzheimer disease because they contribute to the clearance of amyloid-beta (Aβ) peptide." (PMID 37383546, 2023). "In summary, post-ischemic modification of the LRP1 and RAGE genes is useful in the study of the ischemic pathways and molecular factors involved in the development of Alzheimer’s disease." (PMID 38067191, 2023). "Dysregulation of Lrp-1 at the BBB has been shown to contribute to neurotoxic amyloid-β (Aβ) brain accumulation of Aβ in the brain, which drives the Alzheimer’s disease pathology." (PMID 37185751, 2023). "These genes include CACNA1C, LRP1, PLCB2, GRIN2A, and NMUR2, which are involved in pathways such as Alzheimer’s disease, long-term potentiation, calcium signaling, and transmission across chemical synapses." (PMID 29184056, 2017). "LRP1 that binds to LRPAP1 has been shown to be involved in the clearance of the β-amyloid protein, which accumulates in the brain of patients with Alzheimer's disease." (PMID 21603600, 2011). "Low-density lipoprotein receptor-related protein 1 (LRP1) changes in Alzheimer’s disease (AD) patients as compared to non-demented controls (NDC)." (PMID 39065645, 2024). "Clearance of Aβ mediated by lrp-1 at the BBB has been suggested as a potential target for treatment and prevention of Aβ brain accumulation in Alzheimer’s disease, and therefore a better understanding of the lrp-1 expression at the BBB will help in optimizing such a therapeutic strategy." (PMID 37185751, 2023). "After this time, it was noted that Ashwagandha offset the negative effects of Alzheimer’s disease by increasing the number of the LDL receptor-related protein LRP1 (low density lipoprotein related protein 1) in the liver." (PMID 37111543, 2023). "The majority of research focused on LRP1 function has been performed with the aim of understanding amyloid-beta (Aβ) trafficking in the blood–brain barrier (BBB), as LRP1 plays a predominant role in both Aβ production and clearance in Alzheimer’s disease (AD)." (PMID 37408279, 2023). "In this context, age and/or disease-related alterations in LRP1 and LRP2 levels could reduce the efflux of Aβ and concourse to the pathogenesis of Alzheimer’s disease." (PMID 36243724, 2022). "Given the disease relevance of LRP1, not just in vascular disease but also in the pathogenesis of Alzheimer’s disease, further investigation into the mechanism controlling receptor trafficking is warranted." (PMID 33784254, 2021). "Therefore, the strategy of upregulating LRP1, a potentially important therapeutic target of BBB breakdown-related diseases, holds the potential to be used to treat both Alzheimer’s disease and Parkinson’s disease." (PMID 34959306, 2021).
Alzheimer disease (continued). "For instance, as demonstrated in Alzheimer's disease (AD) mouse models, the brain endothelium exhibits significant dysregulation, including upregulated RAGE expression which leads to increased levels of amyloid-β (Aβ) peptides that compete with LRP1-targeting vectors for transcytosis." (PMID 41307200, 2025). "In a mouse model of Alzheimer’s disease, induced by intracerebroventricular (icv) injection of Aβ1-42, daily administration of PRE-084 (1 mg/kg) for 21 days attenuated the amyloid-induced BBB disruption by inhibiting amyloid deposition and increasing expression of LRP-1." (PMID 38791182, 2024). "In summary, although the involvement of Lrp1 in APP and amyloid β processing and Alzheimer’s disease pathogenesis is undeniable, given the complexity of interactions, their true nature may be hidden by the variability in cell lines and the systems used, and is still yet to be fully unraveled." (PMID 30931303, 2019). "Low-density lipoprotein (LDL) receptor-related protein-1 (LRP1, also called α2MR or CD91), a member of the LDL receptor family, is involved in not only lipid metabolism but also various pathophysiologic processes such as Alzheimer’s disease, atherosclerosis, inflammation, and coagulation." (PMID 28589128, 2017).
atherosclerosis (78 papers, 2007 to 2025). A disease characterized by the build-up of fatty material and calcium deposition in the arterial wall resulting in partial or complete occlusion of the arterial lumen. "On the other hand, the LRP1 can cause the accumulation of cholesteryl esters in VSMCs and macrophages, resulting in their transformation into foam cells and the development of atherosclerosis." (PMID 40823653, 2025). "Loss of LRP1 in hematopoietic cells exacerbates atherosclerosis by impairing efferocytosis and increasing lesion area and necrotic core size in high-fat diet-fed atheroprone mice." (PMID 39660125, 2024). "Macrophage LRP1 exports excess cholesterol out of the cell, thus lowering the risk of atherosclerosis." (PMID 37020553, 2023). "Dissimilar LRP1 expression on various monocyte populations have been linked to the development of atherosclerosis and cardio-vascular diseases." (PMID 37020553, 2023). "It has been proposed that decreased LRP1 expression in pro-inflammatory monocytes is linked with development of atherosclerosis." (PMID 37020553, 2023). "Future studies will be needed to clarify the detailed molecular mechanisms by which IL-10 deficiency impairs the LRP1-mediated RCT pathway to promote atherosclerosis." (PMID 36110841, 2022). "Other studies suggest that mice with macrophage-specific low-density lipoprotein-receptor-related protein 1 (LRP1) deficiency or statin treatment showed increased CCR7 expression in lesional macrophages to promote the atherosclerosis regression." (PMID 36012557, 2022). "Taking into account that atherosclerosis is an inflammatory process, additional studies are needed to determine the association between LRP1 expression at cell surface in total monocytes with the atherosclerosis development." (PMID 35958411, 2022). "In summary, we propose that the decreased LRP1 expression at cell surface in total monocytes with pro-inflammatory profile is associated with the development of atherosclerosis in asymptomatic individuals." (PMID 35958411, 2022). "In cultured macrophages, activation of LRP1 induced cell migration, whereas in vivo, LRP1-deficient M1 macrophages more efficiently egressed from atherosclerotic plaques accelerating atherosclerosis regression." (PMID 35202607, 2022). "These mice show reduced plaque CD68+ macrophage numbers and enhanced macrophage CCR7 expression, which contributes to atherosclerosis resolution in addition to the increased reverse cholesterol transport induced by LRP1 deficiency." (PMID 34876704, 2022). "Another study showed a similar result that specific deletion of macrophage LRP1 in the ApoE deficient mice increased atherosclerosis, which is concomitant with the accumulation of apoptotic cells and proinflammatory monocytes in lesions." (PMID 34124208, 2021). "Another cell type with high LRP1 expression and associated with the development of atherosclerosis is adipocytes." (PMID 34124208, 2021). "VSMCs protect the vessels from proteolytic injury caused by atherosclerosis by expressing high levels of anti-plasmin proteins and endocytic LDL-receptor-related protein-1 (LRP-1), which is able to capture aggregated LDL and plasmin–antiplasmin complexes." (PMID 34359938, 2021). "In contrast, LRP1 distal NPxY mutation was shown to improve dyslipidemia and atherosclerosis in ApoE−/− mice." (PMID 33500241, 2021). "In this review, we primarily discuss the role of LRP1 primarily in cells associated with atherosclerosis." (PMID 34124208, 2021). "In line, it has been thoroughly shown that disabling LRP1 tyrosine phosphorylation causes macrophage intracellular lipid accumulation and the anomalous clearance of apoptotic cells, resulting in accelerated atherosclerosis." (PMID 32194867, 2020). "LRP1 has been implicated in several inflammation-associated diseases such as atherosclerosis, certain cancers, and neurodegenerative diseases." (PMID 31511554, 2019).
atherosclerosis (continued). "ApoE-deficient mice exhibit atherosclerosis, while Lrp1 loss from smooth muscle cells enhances vascular cell activation and also leads to atherosclerosis." (PMID 30931303, 2019). "In this study, the authors demonstrated that LRP1-deficient macrophages directly promote reverse cholesterol transport and transition to an anti-inflammatory phenotype, achieving regression of atherosclerosis caused by a Western diet." (PMID 30524198, 2018). "In macrophages, LRP1 helps to export excess cholesterol out of the cell, thus lowering the risk of atherosclerosis." (PMID 29144234, 2017). "Another genetic polymorphism associated with increased risk of atherosclerosis, aortic aneurysms, and vascular dysfunction similar to Marfan syndrome is one affecting the LRP1 gene." (PMID 24312398, 2013). "One year-old apoE-deficient mice having the dysfunctional LRP1 revealed a 3-fold decrease in spontaneous atherosclerosis development and a 2-fold reduction in LDL-cholesterol levels." (PMID 22701627, 2012). "A recent study demonstrated that decreased LRP1 expression in pro-inflammatory monocytes is associated with subclinical atherosclerosis, which may explain the reduced LRP1 levels we observed in early STEMI patients." (PMID 40083817, 2025). "Interestingly, it has been shown that deficiency of macrophage LRP1 leads to a decreased lipoprotein internalization and thus accelerates atherosclerosis progression." (PMID 37020553, 2023). "•Tmsb4x null mice are predisposed to atherosclerosis with dysregulated LRP1 signalling." (PMID 37724952, 2023). "Additionally, LRP1 is implicated in conditions such as neurodegenerative diseases, atherosclerosis, and cancer." (PMID 37020553, 2023). "Taking into account our data, reduced levels of LRP1 at cell surface in circulating monocytes could be considered as a risk factor of atherosclerosis development in asymptomatic individuals." (PMID 35958411, 2022). "Thus, it is possible to prevent the development of atherosclerosis and relieve associated clinical symptoms by regulating LRP1 in adipocytes, including through the use of natural and synthetic LRP1 agonists." (PMID 34124208, 2021). "For instance, it may be possible to use adeno-associated virus-2 (AAV-2) carrying the cDNA of LRP1 or its smaller fragments to increase LRP1 expression in vascular cells to resist atherosclerosis." (PMID 34124208, 2021). "In addition to protecting against atherosclerosis, many studies have also shown that LRP1 overexpression is associated with atherosclerosis progression in both animal and human models of atherosclerosis." (PMID 34124208, 2021). "Similarly, loss of LRP1 on vascular smooth muscle cells (VSMCs) resulted in a dramatic increase in atherosclerosis." (PMID 31080804, 2019). "Therefore, by modulating LXR-driven ABCA1 gene expression through the SHC1/PI3K/AKT/PPARγ/LXRα axis, LRP1 is presenting itself as a pivotal regulator of the metabolic as well as inflammatory processes underlying atherosclerosis." (PMID 29144234, 2017). "However, the fact that LRP1 impairment is associated with decreased atherosclerosis is the most striking finding is this study." (PMID 22701627, 2012). "In addition, although the age is a known risk factor for atherosclerosis development, in our study we observed that the age would be an independent factor for the LRP1 expression in total monocytes since it is decreased in IR group but not in LR group with comparable ages in both groups." (PMID 35958411, 2022). "Thus, the aim of this study was to analyze whether the LRP1 expression level in circulating monocytes from asymptomatic individuals with atherosclerosis is associated with pro-inflammatory phenotypes of these cells." (PMID 35958411, 2022).